IL17A (interleukin 17A)
Diseases named in the same sentence as IL17A in open-access papers (continued):
Sharing a sentence is not in itself a finding about the gene and the disease.
psoriasis (continued). "To investigate the mechanisms of L-THE on IMQ-induced psoriasis in mice, we performed the KEGG pathway enrichment analysis and found that L-THE mainly affected the gene expression profiles of cytokine-cytokine receptor interaction, chemokine signaling pathway, and IL-17A signaling pathway." (PMID 34381369, 2021). "IL-17A-dominant immune activation is also detected in the nonlesional skin of psoriasis." (PMID 32070069, 2020). "Notably, IL-17A is also a potent ROS producer in keratinocytes and recent clinical trials have proven that topical treatment of the antioxidative AHR ligand tapinarof is efficacious for psoriasis." (PMID 32751111, 2020). "TRM cells producing IL-17A in resolved psoriasis epidermis could be associated with early relapse, and CD8+ TRM cells with IL-17A-producing potential in disease-naïve, non-lesional sites possibly correlate with disease duration." (PMID 33633737, 2020). "According to the previous research and clinical experience, several cytokines are released from immune and inflammatory cells during psoriasis, such as TNF-α, IL-17A, and IL-226,14–17, which are speculated to act directly on human keratinocytes and cause a variety of pathological symptoms." (PMID 32076123, 2020). "Moreover, interactions between IL-17A and the PI3K/AKT/mTOR signaling pathway were investigated in several diseases: the effect on autophagy in psoriasis; induced proliferation and migration of glioma cells; the role of lipopolysaccharide (LPS)-induced acute lung injury, etc.." (PMID 33099538, 2020). "Thus, we speculated that RANKL/RANK signaling may improve psoriasis by inhibiting TLR-mediated inflammation and consequently decrease IL-17A production by dermal γδ T cells." (PMID 31659208, 2019). "For moderate to severe psoriasis, several monoclonal antibodies have been approved for the treatment, including tumor necrosis factor-α (TNF-α) inhibitors, an anti-interleukin (IL)-12/23 antibody, anti-IL-23 agents, an IL-17 receptor blocker, and IL-17A inhibitors." (PMID 31881026, 2019). "In 2012, when the role of T cell subsets in psoriasis was not yet fully defined, Krueger and colleagues hypothesized that Th17 cells might be crucial and studied effects of IL-17 inhibition using the anti-IL-17A antibody ixekizumab." (PMID 31673756, 2019). "There are no risk alleles in IL17A, but psoriasis-associated SNPs have been identified in TRAF3IP2, which encodes an IL-17 receptor adaptor while SNPs in IL23A, which encodes p19, are associated with psoriasis susceptibility." (PMID 31130981, 2019). "Although there were few numbers of cells producing IL-17A or IFN-γ in PBS-injected control ears, significant accumulations of the IL-17A+ and IL-17A+IFN-γ+CD4+ T-cell populations were observed in the IL-23–injected ear, as observed in psoriatic dermis of patients with psoriasis." (PMID 29935220, 2019). "This hypothesis is further supported by evidence that IL-17A inhibition alone is highly effective in psoriasis and PsA in the absence of TNF-α inhibition." (PMID 30109481, 2018). "IL-23 injection produces psoriasis-like disease in wild-type mice, but not in IL17 knockout mice, and IL-23-mediated disease could be blocked in wild-type mice by pretreatment with anti-IL-17A antibodies." (PMID 30109481, 2018). "Similarly, we show that also neutrophils isolated from patients with active psoriasis do not express IL-17F, IL-17B, IL-17C, IL-17D, and IL-17E as well as IL-17RC mRNA when activated by R848, IFNγ plus LPS, and IL-17A in vitro." (PMID 29719541, 2018). "Our results confirm that UVB irradiation inhibits IL-17A/TNF-α-induced IL-6, IL-8, and CXCL-1 production in HDFs by decreasing the expression of IL-17RA and IL-17RC on fibroblasts through TGF-β1/Smad3 pathway, which reveals a new mechanism of the therapeutic action of UVB on psoriasis." (PMID 28217129, 2017).
psoriasis (continued). "IL-17C or IL-17RE may therefore be interesting targets for the treatment of psoriasis without increasing susceptibility to CMC, as has been reported for IL-17A directed therapies, albeit at low incidence." (PMID 28590443, 2017). "Our observations on an enhanced caspase-5 regulation in the presence of IL-17A and NLRP1 inflammasome activity in keratinocytes suggests a functional contribution for epidermal IL-1β production in psoriasis and likely other diseases, where Th17 may also contribute, such as lupus erythematosus." (PMID 28422993, 2017). "UVB irradiation inhibits IL-17A/TNF-α-induced IL-6, IL-8, and CXCL-1 production in HDFs by decreasing the expression of IL-17RA and IL-17RC on fibroblasts through TGF-β1/Smad3 signaling pathway, which reveals a new mechanism of the therapeutic action of UVB on psoriasis." (PMID 28217129, 2017). "However, there are instances where IL-17A may be preferred, for example, in patients with higher risk of tuberculosis or in cases with psoriasis with high burden of peripheral arthritis, although extensive psoriasis is not routinely seen in patients with axial SpA." (PMID 28149838, 2017). "Likewise, Th17-driven psoriasis was diagnosed in only two of our patients, each of whom lacked autoantibodies to IL17A, IL17F, and IL22 (our unpublished data)." (PMID 27426947, 2016). "A well designed study proved that inhibition of PKCα pathway using Sorastaurin can stabilize Treg phenotype as evidenced by maintenance of high Foxp3 and CD25 expression, and lack of IL-17A and IFNγ production and has shown efficacy in clinical trials of psoriasis." (PMID 26652024, 2015). "Psoriasis lesions develop as a consequence of abnormal keratinocyte (KC) proliferation, which may be driven by key pro-inflammatory cytokines, including tumor necrosis factor (TNF), interleukin (IL)-17A and IL-23." (PMID 26251673, 2015). "We also assessed functionality of the T cells by evaluating the secretion of several inflammatory cytokines (IL-17A, IFN-gamma, IL-2, IL-33, TNF-alpha, IL-21, IL-22, and IL-27), from cell-sorted purified CD4+ and CD8+ T cells isolated from lesional and unaffected skin biopsies of psoriasis patients." (PMID 23468834, 2013). "Moreover, mRNA levels of IL-17F increased more dramatically than IL-17A, indicating that IL-17F may play a more important role than IL-17A in IMQ-induced psoriasis-like inflammation." (PMID 23825622, 2013). "Interestingly, stimulation of keratinocytes with a combination of IL-17A, IL-22 and TNFα increased S100A7 production, which may form a feed-back loop, amplifying inflammation in psoriasis and other conditions." (PMID 23285311, 2012). "Although IL-17A is expressed on CD4 cells in the animal model of multiple sclerosis, experimental allergic encephalitis, IL-17A is expressed also on other cells, such as macrophages in asthma, CD8 cells in Behcet disease and psoriasis, and mast cells in rheumatoid arthritis synovium." (PMID 21062492, 2010). "Although IL-17A inhibitors were not used in this case, making it difficult to compare the efficacy of IL-17A monotherapy versus IL-17A/F dual inhibition, IL-17 inhibition may represent a rational therapeutic approach for superimposed linear psoriasis." (PMID 40539143, 2025). "In addition, HCRG21 reduced the expression levels of Tnf, Il1β, Il6, Il23a, and Il17a in both psoriatic scab and blood cells and inhibited protein production of IL-23-A and MDC levels compared to the values in the IMQ-induced groups, confirming positive anti-psoriasis dynamics." (PMID 41226679, 2025). "It has been demonstrated that IL-17A stimulates keratinocytes to upregulate the cell cycle-related genes, such as CCNE1, which made contribution to epidermal KC proliferation, therefore we hypothesize that enhanced IL-17 may contribute to the elevated CCNE1 in epidermal cells of psoriasis patients." (PMID 38803495, 2024).
psoriasis (continued). "While Th17 cells and associated molecules, such as IL-17A, IL-17F, IL-22, and tumor necrosis factor (TNF-a), are known to be elevated in serum and psoriatic skin lesions, recent research suggests that Th17 cells are not the primary source of these pathogenic cytokines in psoriasis." (PMID 38791423, 2024). "However, treatment with TET NE could not inhibit the proportion of IL-17A-producing CD4- cells in IMQ-induced psoriasis mice." (PMID 35464441, 2022). "Finally, we showed that splenectomy does not affect a psoriasis-like phenotype on the skin of IMQ-treated mice but could potentiate IMQ-induced increases in IL-17A mRNA in the skin." (PMID 36042262, 2022). "However, the most interesting finding was that guttate psoriasis patients carrying the HLA-Cw6 allele and/or whose flare was produced by S. pyogenes pharyngitis, in comparison to guttate psoriasis patients that did not fulfill those criteria, significantly produced more IL-17A/F by CLA+ T cells." (PMID 34778294, 2021). "In psoriasis, IL-17RA plays a key role in pathogenesis based on: (a) IL-17A, IL-17F, and other IL-17 isoforms are involved in disease development; and (b) IL-17RA is essential for signaling of all IL-17 cytokines but IL-17D, whose receptor has not been identified to date." (PMID 34201664, 2021). "Notably, there was increased IL-17A expression in the gastrointestinal tract of P group post-FMT (p < 0.01), which remained higher than that level of pre-FMT, indicating that the disordered microbial communities of patients with psoriasis sustainably affect the immunity of mice." (PMID 34881280, 2021). "However, looking on the effects of cytokines highly relevant in the pathogenesis of psoriasis, i.e., IL-17A, IL-17F, IL-1α, or TNF, on S100A8 or S100A9 expression in keratinocytes we found strong effects on mRNA induction for both genes most pronounced for IL-17A > IL-17F > IL-1α > TNF." (PMID 33643287, 2020). "Finally, to explore the gene expression profile of IL17A, IL22, and IL23A in relation to other genes expressed in psoriatic plaques, we utilized a machine learning nonlinear dimensionality reduction strategy to visualize the entire psoriasis transcriptome as a 2-dimensional (2D) image." (PMID 31019502, 2019). "Furthermore, as demonstrated in vitro, A-SAA synthesis is stimulated mainly by IL-17A which is overexpressed in psoriasis but not AD skins, that could be accountable for the higher SAA expression levels in psoriasis compared to AD." (PMID 28708859, 2017). "IL-17A mRNA could be detected in T cells, but not in mast cells or neutrophils by quantitative real-time polymerase chain reaction analysis of sorted cell preparations from psoriatic lesions, and IL-17A mRNA was also absent in peripheral blood granulocytes isolated from subjects with psoriasis." (PMID 25828362, 2015). "Although IL-17A, IL-23, and TNF-α are key cytokines in psoriasis, their subcutaneous injection into mice did not induce scratching behavior." (PMID 37834081, 2023). "Although anti-IL-17A monoclonal antibody does not directly target IL-17F, the expression of IL17F was also decreased in the CD161+ T-cell cluster in psoriasis lesional skin after IL-17A blockade (p < 0.05)." (PMID 37781383, 2023). "Concomitantly, psoriasis patients with depression had higher TNF-a, IL-17A, and IL-23 serum levels than those without depression." (PMID 37240864, 2023). "In particular, serum levels of IL-17A were strongly correlated with IL-1α, IL-15, IFN-γ, IL-18, TNF-α, IL-12B, IL-17F, and IL-22 in psoriasis but not in healthy controls." (PMID 36118416, 2022). "Such is the case of ixekizumab, an IL-17A inhibitor which, according to data from a recent RCT, improved depressive symptoms in patients with psoriasis, whereas TNF-α inhibitor etanercept did not, suggesting a particular role of IL-17A in the CNS." (PMID 36291336, 2022).
psoriasis (continued). "Moreover, blockade of the proinflammatory cytokine IL-17a with secukinumab, a fully human selective anti-IL-17a monoclonal antibody, is a valid therapeutic approach and may be useful in the treatment of psoriasis, Rheumatoid Arthritis (RA), and noninfectious uveitis." (PMID 35432162, 2022). "However, none of the models, IL-17A alone (AUC: 0.553, p = 0.5596) or just Claudin-1 (AUC: 0.518, p = 0.8539) or their combination (AUC: 0.559, p = 0.5225), was shown to have better discriminatory performance to discriminate mild psoriasis from moderate-to-severe psoriasis." (PMID 35340911, 2022). "Downregulation of ULK1 with siRNA did not affect the expression of most psoriasis-related cytokines in PHK without stimulation but increased the transcripts of TNF and CXCL8 in the presence of IL-17A." (PMID 34421918, 2021). "Therefore, we speculate that glycyrrhizin reduces the expression of IL-17A by inhibiting the expression of STAT3, while the low expression of IL-17A further weakens the expression of STAT3 in keratinocytes, thereby forming a positive feedback pathway, which is beneficial for improving psoriasis." (PMID 34044769, 2021). "This indicates that IL-19 and IL-24, rather than IL-22, IL-17A or IL-17F, were responsible for the late stage (day 10) keratinocyte hyper-proliferation and acanthosis in the IMQ-induced psoriasis mouse model during anti-IL-10 treatment." (PMID 34616394, 2021). "Anti-IL-22 antibody is not effective in psoriasis, and anti-IL12/23p40 or anti-IL-17A antibodies are not promising as treatment for AD." (PMID 32075269, 2020). "Because IL22 failed to strongly correlate with IL17A and IL23A, the relationships between IL22 and keratin genes were explored across the four independently acquired RNA-Seq psoriasis datasets." (PMID 31019502, 2019). "Further in vivo study with IMQ‐induced psoriasis mice indicates that nor@MSC‐EVs alleviate erythema, scaling, and thickness of skin lesions, showing a more potent therapeutic effect than the currently used clinical bioreagent anti‐IL17A." (PMID 39665264, 2025). "hs-CRP, IL-17A, and TNF-α in healthy controls, psoriasis patients with and without atherosclerosis." (PMID 39104857, 2024). "While, in the pathological environment of psoriasis, whether HMGB1 can exert the regulatory effect on IL‐17A is not clear." (PMID 38414294, 2024). "Increased expression of genes induced by IL-17A in keratinocytes and TCR genes, including genes previously determined to be a part of the PSTR or present as a psoriasis molecular scar, was more efficiently normalized by guselkumab than by ADA at all time points assessed." (PMID 39114670, 2024). "In terms of cytokine production, both CD49a+ and CD49a-CD103+CD8+ TRM cells produced high levels of IFN-γ but not IL-17A in vitiligo patients, whereas CD49a+ and CD49a-CD103+CD8+ TRM cells produced high levels of IFN-γ and IL-17A, respectively, in patients with psoriasis." (PMID 39193473, 2024). "In the same study, TNF-a, IL-17A, and IL-12 (but not IL-23) serum levels were positively correlated with HADS anxiety (HADS-A) scores, while psoriasis patients with anxiety had increased serum TNF-a and IL-17A compared to those without the psychologic comorbidity." (PMID 37240864, 2023). "Therefore, we introduced a novel combination of cytokines, including IL-17A, IL-22, IFN-γ, TNF-α, and KGF as a CytoMix, that had not been previously applied for inducing psoriasis-like inflammation." (PMID 38132145, 2023). "Notably, both serum IL-17A and Claudin-1 do not correlate with PASI in psoriasis and in its subgroups, except for correlation in late-onset psoriasis." (PMID 35340911, 2022). "In FFA4 KO mice, the levels of inflammatory TH23/TH17 axis cytokines (IL-17A, IL-22 and IL-23) and TH1 cytokines (IL-1β, IFN-γ and TNF-α) in the lymph nodes were also increased after psoriasis induction; however, Compound A treatment did not suppress the cytokine levels." (PMID 35562873, 2022).
psoriasis (continued). "Patients with moderate-to-severe psoriasis and CVD had lower levels of IL-17A compared to those without CVD (normalized protein expression [NPX] 2.02 vs. 2.55, p = 0.013), and lower IL-17A levels (NPX < 2.3) were associated with higher incidence of CVD (OR = 24.5, p = 0.0028, 95% CI 2.1–1425.1)." (PMID 35008981, 2022). "Interestingly, IL-9 partially enhanced SE-induced IL-17A, but not IFN-γ, secretion by CLA+ T cells, as well as it promoted the survival of the skin-homing T cell subset in psoriasis." (PMID 34778294, 2021). "We found that CD8αα+T cells could produce IL‐17A and IFN‐γ in lesions of patients with psoriasis but did not express these cytokines in normal skin." (PMID 35663772, 2021). "It was previously reported that the inflammatory cytokine IL-17A is important in both human psoriasis and IMQ-induced skin inflammation, and the ear edema induced by topical application of IMQ was significantly attenuated in IL-17A knockout mice (data not shown)." (PMID 33836731, 2021). "Interestingly, CD8+ T cells infiltrating HS skin did not make appreciable amounts of IL-17A, whereas CD4+ Tcons in lesional HS skin produced similar levels of this cytokine to that of psoriasis." (PMID 32841223, 2020). "In addition, studies examining the effect of salt in psoriasis (but also in spondyloarthritis including psoriatic arthritis), an IMD with a strong Th17/IL-17A involvement, are currently lacking." (PMID 29740348, 2018).